ANGPT2 (angiopoietin 2)
Diseases named in the same sentence as ANGPT2 in open-access papers (continued):
Sharing a sentence is not in itself a finding about the gene and the disease.
acute myocardial infarction (6 papers, 2013 to 2021). Necrosis of the myocardium, as a result of interruption of the blood supply to the area. "ANGPT2 is associated with a greater risk of cardiovascular mortality in the general population, as well as with higher mortality in patients suffering from myocardial infarction and cardiogenic shock." (PMID 32575548, 2020). "In the remodeling phase after myocardial infarction, endothelial- and macrophage-derived ANGPT2 promotes abnormal vascular remodeling and exacerbates inflammation." (PMID 32575548, 2020). "ANGPT2 has been proposed as a prognostic biomarker of adverse cardiovascular events in myocardial infarction and after percutaneous coronary intervention (PCI)." (PMID 32575548, 2020). "In a multicenter, prospective, observational study, sTM and protein C were shown to be predictable markers of AKI in critical care settings, whereas in another study, sTM and angiopoietin-2 were shown to play important roles in the development of AKI in patients with acute myocardial infarction." (PMID 28841902, 2017). "Importantly, specific ANGPT2 deletion or the use of an anti-ANGPT2 antibody markedly reduced cardiac hypoxia, proinflammatory macrophage polarization, adverse vascular remodeling, and the consequent progression of HF after myocardial infarction in mice." (PMID 32575548, 2020). "The first and also the most important limitation is that we cannot demonstrate the specificity of ANGPT2 to diagnose AAD from other diseases, especially in patients with chest pain mimicking AAD such as acute myocardial infarction or pulmonary embolism." (PMID 35004874, 2021). "Elevated circulating levels of ANGPT2 have been reported in acute coronary syndromes, and this mediator has been proposed as a negative prognostic marker after myocardial infarction and PCI." (PMID 32575548, 2020).
age-related macular degeneration (6 papers, 2023 to 2025). Age-related loss of vision in the central portion of the retina (macula), secondary to retinal degeneration. "Faricimab, a bispecific antibody targeting both VEGF-A and angiopoietin-2 (Ang-2), has shown promising results in age-related macular degeneration and diabetic macular edema." (PMID 40665457, 2025). "We conducted a systematic review and meta-analysis to evaluate the visual, anatomical, and safety outcomes of the intravitreal faricimab, a novel vascular endothelial growth factor (VEGF)/angiopoietin-2 (Ang-2) bispecific agent, in neovascular age-related macular degeneration (nAMD) patients." (PMID 38291069, 2024). "Finally, faricimab, an antibody against vascular endothelial growth factor A and, in addition, angiopoietin-2, is a new option for the treatment of age-related macular degeneration." (PMID 37278927, 2023). "Faricimab, Neovascular Age-Related Macular Degeneration (nAMD), Intravitreal Injections, Best-Corrected Visual Acuity, Phase 3 Trials, Aflibercept, Ocular Adverse Events, Non-Inferiority, Angiopoietin-2, Vascular Endothelial Growth Factor A (VEGF-A), Treatment Regimens, TENAYA, LUCERNE." (PMID 40428167, 2025).
cerebral malaria (6 papers, 2012 to 2025). A sequestration of Plasmodium falciparum in the brain, which can cause coma and/or seizures. "In addition, angiopoietin 2 (Ang-2) and its tyrosine-kinase-receptor 2 (Tie-2) were found to be increased and associated with retinopathies in Malawian children with cerebral malaria." (PMID 35204613, 2022). "Patients with cerebral malaria frequently exhibit markedly high Angiopoietin-2–Angiopoietin-1 ratios, reflecting profound endothelial activation." (PMID 41002937, 2025). "Angiopoietin-2 (Ang-2) is higher and Angiopoietin-1 (Ang-1) is lower in cerebral malaria (CM) than in uncomplicated malaria, according to several studies." (PMID 41002937, 2025). "Compared to healthy controls, cerebral malaria patients have been shown to have reduced levels of angiopoietin 1 (ANG1), elevated levels of angiopoietin 2 (ANG2) and higher ANG2/1 ratios; moreover, low ANG1 levels at presentation predicted subsequent mortality in children with cerebral malaria." (PMID 26979504, 2016).
cervical cancer (6 papers, 2017 to 2024). A primary or metastatic malignant neoplasm involving the cervix. "Interestingly, we observed a reciprocal change in angiopoietin-1 and angiopoietin-2 transcripts in endothelial cells treated with cervical cancer exosomes and shifting of the angiopoietin balance towards angiopoietin-2." (PMID 34167524, 2021). "Macrophages carrying TIE2 (TEMs) interact with angiopoietin-2 (ANG2), ultimately promoting cervical cancer angiogenesis." (PMID 39148736, 2024). "HUVEC treated with HPV-positive cervical cancer exosomes showed an increased transcript level of VEGF-A, VEGFR2, and angiopoietin-2." (PMID 34167524, 2021).
diabetic macular edema (6 papers, 2023 to 2025). "Conditions like neovascular age-related macular degeneration and diabetic macular edema could be successfully treated by inhibiting ANGPT2." (PMID 37616050, 2023). "In 2022 US-FDA-approved a new anti-VEGF agent Faricimab with an additional angiopoietin-2 inhibitory effect to treat wet AMD and Diabetic macular edema (DME)." (PMID 39936369, 2025). "In patients with diabetic macular edema (DME) from YOSEMITE/RHINE, dual angiopoietin-2/vascular endothelial growth factor-A (VEGF-A) inhibition with faricimab resulted in visual/anatomic improvements with extended dosing." (PMID 39388397, 2024).
falciparum malaria (6 papers, 2011 to 2025). "In falciparum malaria, clinical severity and mortality are also independently associated with impaired microvascular function and with increased angiopoietin-2 (Ang-2), a key product of endothelial Weibel-Palade Bodies (WPB) and an autocrine mediator of endothelial activation." (PMID 25569250, 2015). "Plasma concentrations of a key autocrine mediator of endothelial activation, angiopoietin-2 (Ang-2), correlate with later death in falciparum malaria in both adults and children." (PMID 26018532, 2015).
oral squamous cell carcinoma (6 papers, 2013 to 2024). "Previous studies have showed that expression of angiopoietin-2 was significantly associated with angiogenesis and vessel maturation in oral squamous cell carcinoma (SCC)." (PMID 32799882, 2020). "The study has shown that compared with the healthy oral mucosa, angiopoietin-2 is overexpressed and angiopoietin-1 is downregulated in tumor samples of oral squamous cell carcinoma." (PMID 32799882, 2020). "Interestingly, CCL4 has been found to promote p-MEK, p-ERK1/2, and p-STAT3 activation, leading to increased angiopoietin 2 expression, thereby facilitating angiogenesis in oral squamous cell carcinoma." (PMID 38739303, 2024). "Importantly, overexpression of angiopoietin 2 accelerated the carcinogenesis of oral squamous cell carcinoma through promoting epithelial-mesenchymal transition-induced angiogenesis." (PMID 32799882, 2020).
pneumonia (6 papers, 2022 to 2026). An acute, acute and chronic, or chronic inflammation focally or diffusely affecting the lung parenchyma, caused by an infection in one or both of the lungs (by bacteria, viruses, fungi, or mycoplasma.). "In burn patients, an early elevation in Angiopoietin-2 and an imbalance of the Angiopoietin-2/1 ratio correlate with the development of pneumonia." (PMID 41562699, 2025). "We thus validated ANGPT2 targeting in our human models and tested the correlations of miR-1 in our pneumonia cohort." (PMID 37737266, 2023). "The levels of IL-6, procalcitonin, sRAGE, and angiopoietin-2 were lower post-event compared to the day of pneumonia diagnosis, while syndecan-1 and angiopoietin-1 concentrations were higher post-event; the other host response biomarkers remained unaltered." (PMID 37415223, 2023). "We validated miR-1–mediated regulation of ANGPT2 in both mouse and human ECs and found that in a 119-patient pneumonia cohort, miR-1 correlated inversely with ANGPT2." (PMID 37737266, 2023).
renal cell carcinoma (6 papers, 2005 to 2020). "For example, the oncogenes of renal cell carcinoma, ANGPT2, and NEDD9, are the targets of miR-145, which is involved in tumor progression by suppression of the two oncogenes expression." (PMID 32404179, 2020). "Similarly to previous observations of induced angiopoietins in primary renal cell carcinomas (ANGPT2 8.18-fold induced and ANGPTL4 18–32-fold induced, we found both ANGPTL4 induction (2.09 fold, Pcorr < 2e-9), and ANGPT2 induction (2.23-fold Pcorr < .005)." (PMID 15836779, 2005).
atrial fibrillation (5 papers, 2023 to 2026). A disorder characterized by an electrocardiographic finding of a supraventricular arrhythmia characterized by the replacement of consistent P waves by rapid oscillations or fibrillatory waves that vary in size, shape and timing and are accompanied by an irregular ventricular response. "ANGPT2 is primarily considered a vascular and angiogenic marker, whereas BMP10 is highly cardiac-specific, especially related to atrial tissue and atrial fibrillation risk." (PMID 40823165, 2025).
Cirrhosis (5 papers, 2013 to 2025). A chronic disorder of the liver in which liver tissue becomes scarred and is partially replaced by regenerative nodules and fibrotic tissue resulting in loss of liver function. "We demonstrated that HPS in PSVD is characterized by high plasma concentration of angiogenic mediators (Angiopoietin 2, ICAM3, and Tie2), similarly to what happens in cirrhosis." (PMID 40171298, 2025). "Messenger RNA (mRNA) expression levels of the angiopoietin genes (ANGPT1 and ANGPT2) involved in vessel maturation are altered, with the ANGPT1/ANGPT2 ratio increased compared with normal liver, cirrhosis, and other liver tumors." (PMID 23691331, 2013). "In this regard, increased plasma concentrations of several angiogenic mediators, including angiopoietin 2, TEK tyrosine kinase endothelial (Tie2), intercellular adhesion molecule 3 (ICAM3), and vascular cell adhesion molecule 1 (VCAM1), are increased in patients with HPS and cirrhosis." (PMID 40171298, 2025). "In both PSVD and cirrhosis, patients with HPS had higher plasma concentrations of ICAM3 and Angiopoietin 2 than those without HPS." (PMID 40171298, 2025).
dengue (5 papers, 2016 to 2025). "Finally, low levels of angiopoietin 1 (Ang1) and elevated levels of its antagonist angiopoietin 2 (Ang2) have been associated with dengue vascular leakage, and the Ang1/Ang2 ratio has been proposed as a diagnostic marker for patients at risk of developing severe dengue." (PMID 32759331, 2020). "The interaction of the NS1 protein with the glycocalyx and angiopoietin-2, analogous to what is seen in dengue fever, may be an explanation." (PMID 37757571, 2023). "This differs from other endothelial biomarkers such as angiopoietin-2 and VCAM-1 that tend to peak during the critical phase and suggests that hypoargininemia, high arginase, and reduced NO bioavailability are some of the earliest abnormalities in the pathophysiology of dengue." (PMID 28673038, 2017).
endometriosis (5 papers, 2019 to 2024). The growth of functional endometrial tissue in anatomic sites outside the uterine body. "However, up to now, the underlying mechanism for ANGPT2 affecting the pathogenesis of endometriosis is still unclear." (PMID 31547870, 2019). "We further investigated whether there was an association between the expression of ANGPT2 and miR-205-5p in human endometriosis tissues." (PMID 31547870, 2019). "The newly identified miR-205-5p-ANGPT2-AKT/ERK axis illustrates the molecular mechanism of endometriosis progression and may represent a novel diagnostic biomarker and therapeutic target for disease treatment." (PMID 31547870, 2019). "For instance, miR‐205‐5p was found to be a novel suppressor of endometriosis through activating the ERK/AKT pathway by sponging ANGPT2 in ESCs." (PMID 33372387, 2021). "The dysmenorrhoea score, CA125 level, and endometriosis score were dramatically correlated with downregulation of miR-205-5p and upregulation of ANGPT2." (PMID 31547870, 2019). "More importantly, our clinical data showed that both miR-205-5p and ANGPT2 are valuable factors for reflecting the severity of endometriosis." (PMID 31547870, 2019). "Taken together, these data indicated that miR-205-5p and ANGPT2 were promising biomarkers for reflecting the severity of endometriosis." (PMID 31547870, 2019). "More importantly, we showed that clinical endometriosis severity scores are also closely correlated with miR-205-5p and ANGPT2 expression, and predicting endometriosis severity was also determined according to the multivariate regression model." (PMID 31547870, 2019). "Collectively, these results indicated that ANGPT2 was a critical downstream mediator of miR-205-5p suppressive effects in endometriosis." (PMID 31547870, 2019). "More importantly, multivariate analysis confirmed that downregulation of miR-205-5p and upregulation of ANGPT2 score were also markedly correlated with endometriosis score." (PMID 31547870, 2019). "Both heparinase (Hpa) and angiopoietin 2 (Ang-2) are expressed in endometriosis." (PMID 39062484, 2024). "miR-205-5p via ANGPT2/ ERK/AKT axis in endometrial stromal cells could inhibit human endometriosis progression." (PMID 32850438, 2020). "The results showed that the expression of ANGPT2 protein was negatively correlated with miR-205-5p levels in the EC tissues, suggesting that miR-205-5p suppressed ANGPT2 expression in clinical endometriosis progression." (PMID 31547870, 2019). "Moreover, activation of the AKT and ERK pathways involved in endometriosis progression was responsible for the downregulation of miR-205-5p and upregulation of ANGPT2." (PMID 31547870, 2019). "The newly identified miR-205-5p-ANGPT2-AKT/ERK signalling axis illustrated a critical molecular mechanism of endometriosis progression and provided a novel diagnostic and therapeutic target for endometriosis treatment." (PMID 31547870, 2019). "Importantly, the miR-205-5p-ANGPT2 axis was found to activate the ERK/AKT pathway in endometriosis." (PMID 31547870, 2019). "Finally, miR-205-5p and ANGPT2 expression were closely correlated with the endometriosis severity." (PMID 31547870, 2019). "The roles of miR-205-5p and its candidate target gene, angiopoietin-2 (ANGPT2), in endometriosis progression were confirmed on the basis of both in vitro and in vivo systems." (PMID 31547870, 2019). "We further confirmed that miR-205-5p could directly target angiopoietin-2 (ANGPT2) by binding to its 3′-UTR and be involved in the procession of endometriosis via regulating the ANGPT2 pathway." (PMID 31547870, 2019).
Insulin resistance (5 papers, 2011 to 2022). Increased resistance towards insulin, that is, diminished effectiveness of insulin in reducing blood glucose levels. "Thus, stimulation of FA transport by targeting SAT endothelium through Angpt2–integrin α5β1 signaling offers a new therapeutic avenue for combat against ectopic lipid-induced insulin resistance and related metabolic syndrome." (PMID 32532986, 2020). "Moreover, ANGPT-2 levels were associated with a 2.83-fold higher risk of T2DM and were positively correlated with fasting blood glucose, HbA1c, homeostatic model assessment of insulin resistance (HOMA-IR), triglycerides, and LDL cholesterol." (PMID 34762787, 2021). "Even current finding has shown the pivotal role of another angiogenic regulator, angiopoietin 2 (ANGPT2), in modulating FAT/CD36 and FATP3 expression through integrin α5β1 signaling and key to insulin resistance." (PMID 34529222, 2022). "Adipocyte-specific deletion of Angpt2 markedly reduced fatty acid uptake and storage in SAT, leading to ectopic lipid accumulation in glucose-consuming organs including skeletal muscle and liver and to systemic insulin resistance." (PMID 32532986, 2020). "However, this correlation was lost after correction for T2D and insulin resistance and plasma ANGPT2 levels were not related to NAFLD features." (PMID 34638880, 2021).
liver cancer (5 papers, 2017 to 2022). An epithelial or non-epithelial malignant neoplasm that arises from the liver. "Again, ANGPT2 (angiopoietin-2) as a prognostic marker plays a pivotal role in liver cancer and concomitantly with ANGPT1 (angiopoietin-1) and VEGF (vascular endothelial growth factor) promoted activity hypervascularity." (PMID 35163556, 2022). "Exosomes derived from liver cancer cells carry angiopoietin 2 (ANGPT2), which is transported to vascular endothelial cells through exosomal endocytosis, resulting in a significant increase in angiogenesis." (PMID 33854614, 2021). "A prospective study shows that angiogenesis-related genes, including ANGPT2, are independent factors that correlate with the tumor progression and prognosis of liver cancer patients." (PMID 32644941, 2020).
lymph node metastasis (5 papers, 2017 to 2022). "Next, ANGPT2 alleles in patients with malignant breast neoplasms were examined to clarify the role of ANGPT2 polymorphisms in clinical stage, primary tumor size, lymph node metastasis, distant metastasis, and pathological grade." (PMID 36008514, 2022). "We also illustrated that high ANGPT2 was linked to lymph node metastasis both at mRNA and protein levels." (PMID 31892982, 2020). "ANGPT2 expression, lymph node metastasis, as well as TNM stage were obviously associated with the clinical outcomes of ADC patients." (PMID 31892982, 2020). "The meta-analysis demonstrated that the mRNA level of ANGPT2 was dramatically higher in ADC patients with lymph node metastasis (OR=1.58, 95% CI: 1.18-2.12, P=0.524, and I2=0.0%)." (PMID 31892982, 2020). "Division of these patients into ANGPT2-high and low expression groups by median IHC score 8 revealed a strong relationship with lymph node metastasis (P=0.002)." (PMID 31892982, 2020). "High angiopoietin-2 and TGF-β1 levels were significantly correlated with late TNM stages (stage III-IV) (OR = 4.846, 5.333; p < 0.05) and only a high TGF-β1 level was associated with metastasis (OR = 3.467; p = 0.024) and lymph node metastasis (OR = 3.111)." (PMID 33806004, 2021). "Thus, hematogenous metastatic spread and the development of pulmonary metastases were associated with high expression of ANGPT2, F3, and TIE1, whereas lymphogenous metastatic spread and the development of lymph node metastases were associated with high expression of NRP2." (PMID 29017512, 2017).
lymphedema (5 papers, 2020 to 2024). Excess fluid collection in tissues, causing swelling. "In humans, similar to PIEZO1, mutations in FLT4, ANGPT2, and TIE1 have been associated with lymphedema, underscoring the conservation of function across species." (PMID 38747287, 2024).
myeloma (5 papers, 2013 to 2025). "In the course of multiple myeloma, the ANGPT2 factor plays an important role." (PMID 40115011, 2025). "In the presence of hypoxic conditions, myeloma cells upregulate hypoxia induced factor 1α (HIF1α), which regulates transcription of pro-angiogenic cytokines including HGF, bFGF, VEGF, and Angiopoietin-2 (Ang-2)." (PMID 33634031, 2020). "Higher levels of ANGPT2 protein in people with multiple myeloma have a negative effect on the general condition of the patient because it promotes disease progression." (PMID 40115011, 2025). "Many angiopoietins, such as basic fibroblast growth factor(bFGF) and angiopoietin-2 (Ang-2), were found to correlate with VEGF and cEPCs in MMpatients; therefore, the addition of an anti-angiopoietin agent may improve the efficacyof anti-myeloma therapy." (PMID 26108099, 2015).
neovascular age-related macular degeneration (5 papers, 2017 to 2024). "Angiopoietin 2 (ANG2) is a proangiogenic cytokine which may have an implication in neovascular age related macular degeneration (nAMD)." (PMID 28345626, 2017).